TRPM6 (transient receptor potential cation channel subfamily M member 6)
Diseases named in the same sentence as TRPM6 in open-access papers (continued):
Sharing a sentence is not in itself a finding about the gene and the disease.
Hypomagnesemia (continued). "Diminished active Magnesium transport in the colon, primarily mediated by the ion channels TRPM6 and TRPM7, serves as the principal explanation for proton pump inhibitor-related hypomagnesemia." (PMID 40291321, 2025). "Several clinical and experimental studies have proposed that TRPM6 activity is affected by PPI use, resulting in PPI-induced hypomagnesemia." (PMID 39266724, 2025). "TRPM6 and − 7 are both involved in the human disease HOMG1 (intestinal hypomagnesemia with secondary hypocalcemia)." (PMID 39614204, 2024). "The EGFR pathway is inhibited by anti-EGFR antibodies, which leads to an inhibition of magnesium reabsorption by transient receptor potential cation channel, subfamily M, member 6 (TRPM6) in the renal tubules, accompanying hypomagnesemia." (PMID 31637554, 2019). "Mice lacking Trpm6 in the whole body or specifically in the intestine exhibited severe hypomagnesemia and depletion of Mg2+ in bones due to impaired intestinal uptake of Mg2+ ions." (PMID 41118703, 2025). "We showed that DBA/2 mice had functional hypomagnesemia regardless of their fetuin-A genotype due to altered expression of magnesium transporter Trpm6, which mediates intestinal absorption and kidney reabsorption of magnesium, respectively." (PMID 32074140, 2020). "Previous studies have found that renal excretion of magnesium is reduced appropriately in patients with PPI-induced hypomagnesemia, and that a PPI-induced decrease in the luminal pH of the intestine might alter the TRPM6/7 channel’s affinity for magnesium." (PMID 25394217, 2014). "TRPM6 mRNA was downregulated but not the TRPM6 protein level, indicating that the hypomagnesemia is due to the inactivation of TRPM6 at protein level." (PMID 23457647, 2013). "We hypothesize that the mechanism leading to hypomagnesemia is similar in rats treated with cisplatin and rats treated with CNI and is related to a decreased expression of the renal Mg2+ channel TRPM6." (PMID 23457647, 2013). "Interestingly, TRPM6± mice showed reduced expression of the channel in kidney and colon, resulting in mild hypomagnesemia with no hypocalcemia." (PMID 29686978, 2018). "However, the stimulatory effect of EGF on TRPM6 activity could be diminished by preincubation of cetuximab, an EGFR blockade, thus affecting Mg2+ transport and leading to hypomagnesemia." (PMID 25542231, 2015). "In mice, maternal hypomagnesemia did not change the activity of TRPM7 and TRPM6 ion channels but increased the expression of placental MagT1 transporter and Ca-selective channels (TRPV6), which probably increases the levels of Mg in the placenta and maintains its function in Mg deficiency." (PMID 30717440, 2019).
Hypocalcemia (37 papers, 2009 to 2026). An abnormally decreased calcium concentration in the blood. "Mutations in the TRPM6 gene, which encodes the epithelial Mg channel, result in secondary hypocalcemia; changes in renal function also affect Mg levels." (PMID 39071492, 2024). "Mutations in TRPM6, which plays a role in magnesium and Ca2+ homeostasis, can lead to hypomagnesemia with secondary hypocalcemia." (PMID 37894842, 2023). "Mutations in Trpm6 lead to lower Mg2+ absorption despite hypomagnesemia, along with secondary hypocalcemia (HSH), and physiological intracellular Mg·ATP and Mg2+ levels are potent negative feedback inhibitors of TRPM6 channel permeability." (PMID 36110961, 2022). "We also found that mutations in TRPM6 can lead to ion channel dysfunction causing primary hypomagnesaemia and secondary hypocalcaemia." (PMID 35493463, 2022). "In this context, mutations in TRPM6 (encoding a transient receptor potential cation channel) cause hypomagnesaemia with secondary hypocalcaemia." (PMID 29769070, 2018). "Hereditary hypomagnesemia with secondary hypocalcemia (HSH) is a rare autosomal recessive disease caused by mutations in the transient receptor potential melastatin 6 (TRPM6) gene." (PMID 26759217, 2016). "In humans, mutations in the TRPM6 gene lead to hypomagnesaemia with secondary hypocalcaemia (HSH), an autosomal recessive condition characterized by excessive renal magnesium wasting." (PMID 25692682, 2015). "Mutations in TRPM6 on chromosome 9q22 not only cause hypomagnesaemia, but can cause hypomagnesaemia with secondary hypocalcaemia (HSH), a syndrome with autosomal recessive inheritance." (PMID 25138239, 2015). "Another key molecule is TRPM6; mutations of TRPM6 cause recessive hypomagnesemia with secondary hypocalcemia." (PMID 24339795, 2013). "Rare mutations in TRPM6 are a cause of autosomal recessive hypomagnesemia with secondary hypocalcemia (OMIM #602014)." (PMID 20700443, 2010). "Rare mutations in TRPM6, either incomplete or complete loss-of-function, have been associated with cases of autosomal-recessive hypomagnesemia with secondary hypocalcemia." (PMID 19149903, 2009). "Several loss-of-function mutations in TRPM6 have been identified among patients with autosomal-recessive familial hypomagnesemia with secondary hypocalcemia." (PMID 19149903, 2009). "The single genetic variant used in functional analyses on the TRPM6 gene is primarily involved in magnesium transport across the intestinal lumen and distal convoluted tubule, with variations associated with hypomagnesaemia and secondary hypocalcaemia." (PMID 39519523, 2024). "TRPM6 exhibits a restricted expression profile with high expression rates in intestine, lung, and kidney and its mutations have been associated with hypo-magnesia with secondary hypocalcemia." (PMID 37894842, 2023). "Mutations in TRPM6 cause hypomagnesaemia with secondary hypocalcaemia (HOMG1/HSH; MIM# 602014)." (PMID 33859252, 2021). "Mutations in TRPM6 are the main cause of hypomagnesemia with secondary hypocalcemia." (PMID 32643506, 2020). "The similar clinical presentation between familial isolated hypoparathyroidism in humans and equine idiopathic hypocalcemia led to the hypothesis that a coding variant within PTH, GCM2, CASR, GNA11 or TRPM6 would be associated with idiopathic hypocalcemia of TB foals." (PMID 32986719, 2020). "TRPM6 and 7 are involved in HOMG1, characterized by hypomagnesemia with secondary hypocalcemia and is associated with calcinosis (stones) in several organs, including kidneys." (PMID 39614204, 2024). "In individuals with variants in TRPM6 and TRPM7, encoding Mg2+ channels crucial for uptake of Mg2+ in the DCT and other tissues, it has been shown that hypocalcaemia can occur secondary to hypomagnesaemia." (PMID 38519529, 2024). "In humans, mutations in TRPM6 cause familial hypomagnesemia with secondary hypocalcemia (OMIM #607009), and a TRPM6 variant has been associated with meningomyelocele." (PMID 37377737, 2023).
Hypocalcemia (continued). "Another gene, transient receptor potential channel melastin 6 (TRPM6), has been reported to promote hypomagnesemia with secondary hypocalcemia in human patients." (PMID 32986719, 2020). "Genetic analyses of patients with autosomal-recessive hypomagnesemia and secondary hypocalcemia (HSH) indicate that TRPM6 is an essential gene for magnesium homeostasis." (PMID 25692682, 2015). "Similarities between familial isolated hypoparathyroidism in humans and the refractory hypocalcemia observed in Thoroughbred foals led to the hypothesis that genetic variants in PTH, GCM2, CASR, GNA11 or TRPM6 may be responsible for the disease in the horse." (PMID 32986719, 2020). "In addition, mutations in the TRPM6 gene were also discovered in patients of non-tumor diseases, such as hypomagnesemia with secondary hypocalcemia." (PMID 26870154, 2015). "Although there is no research data verifying that TRPM7 is directly related to secondary hypocalcemia, the proteins of TRPM6 and TRPM7 have a high sequence similarity and the TRPM6/TRPM7 hetero-oligomerization plays a role in TRPM6-mediated epithelial magnesium absorption." (PMID 32643506, 2020).
diabetes (11 papers, 2009 to 2025). "Intriguingly, most of the identified genes, which showed strong signals in normal islets but were potently suppressed by STZ, were previously linked with important β-cell functions or diabetes development, such as Slc2a2, Ucn3, Gad1, Cox6a2, Trpm6 and Vdr." (PMID 23828045, 2013). "Only among women with low magnesium intake was the haplotype based on 2SNPs in TRPM6 significantly associated with diabetes risk, although statistical power in our subgroup analyses became weak." (PMID 19149903, 2009). "Genetics seems to be a vital risk factor for Type 2 diabetes, and serum magnesium levels may modify the risk of diabetes through several magnesium-regulating genes such as TRPM6, CLDN19, SLC41A2, CNNM2, and FXYD2." (PMID 35565766, 2022). "However, the authors observed suggestive inverse association of rs2274924 and rs3750425 in TRPM6 with fasting glucose, the same loci associated with risk of diabetes in women when in haplotype, and with risk of gestational diabetes." (PMID 24322525, 2013). "Individuals with both rare alleles, whose TRPM6 channel function is deficient in magnesium absorption, may be more prone to magnesium deficiency through low intake and in turn to an increased risk of diabetes." (PMID 19149903, 2009). "Similar effects occur with insulin, which increases the activity and recruitment of TRPM6, being abolished by diabetes treatment drugs." (PMID 33291725, 2020). "Genetic variation in CLDN19, CNNM2, FXYD2, SLC41A2, and TRPM6 significantly influenced diabetes risk (p < 0.05), and for CNNM2, FXYD2, SLC41A2 and TRPM6 this risk was completely mediated by serum magnesium levels." (PMID 28224192, 2017). "We, hereby, replicate the findings from previous studies on the effect of TRPM6, SLC41A2 and CLDN19 on diabetes risk." (PMID 28224192, 2017). "The non-significant findings which nevertheless show some consistency with concurrent and prior work in this area, lend further plausibility to a role for TRPM6 in glycemia and diabetes." (PMID 24322525, 2013). "Neither was there any evidence of association between common TRPM6 and TRPM7 haplotypes and diabetes risk." (PMID 19149903, 2009). "We analyzed 20 haplotype-tagging single nucleotide polymorphisms (SNPs) in TRPM6 and 5 common SNPs in TRPM7 for their association with diabetes risk." (PMID 19149903, 2009). "For example, genetic variants in TRPM6 are associated with the development of gestational diabetes and type 2 diabetes and SNPs in CNNM2, SLC41A2, and TRPM6 were associated with the risk of diabetes through serum Mg2+ levels." (PMID 38279093, 2024). "In healthy people, insulin would regulate TRPM6 channel activity, but this may be impaired in diabetes." (PMID 38279093, 2024). "Furthermore, common genetic variation in magnesium regulating genes TRPM6, CLDN19, SLC41A2, CNNM2 and FXYD2 significantly modify the risk of diabetes through serum magnesium levels." (PMID 28224192, 2017). "Thus, it is important to further examine in human population data whether magnesium intake modifies any common genetic effects of TRPM6 and TRPM7 on diabetes risk." (PMID 19149903, 2009).
Insulin resistance (6 papers, 2020 to 2025). Increased resistance towards insulin, that is, diminished effectiveness of insulin in reducing blood glucose levels. "The improvement of insulin resistance observed after SGLT2 inhibitors administration is probably associated with a restored activity of TRPM6 and a consequently reduced magnesium excretion." (PMID 32549243, 2020). "On the other hand, increased urinary magnesium may be associated with insulin resistance due to the decreased activity of the transient receptor potential melastatin type 6 (TRPM6) cation channel in distal renal collecting tubules." (PMID 35872985, 2022). "The mechanism of increased excretion, as with insulin resistance, is likely a downregulation of TRPM6, which leads to a decreased distal reabsorption of magnesium." (PMID 39911868, 2025). "SGLT-2is reduce the circulating insulin levels and improve insulin resistance, possibly leading to an increased TRPM6 activity and a reduced urinary magnesium excretion." (PMID 35872985, 2022). "Insulin resistance could reduce the TRPM6 channel activity of the intestinal and renal tubular epithelium and reduce the absorption of magnesium in the intestinal and renal epithelium, resulting in low serum magnesium." (PMID 36203780, 2022).
type 2 diabetes (6 papers, 2009 to 2024). "People with type 2 diabetes often have hypermagnesiuria, which is a fractional excretion of Mg2+ (FEMg) above 4%, which is suggested to be caused by reduced Mg2+-channel TRPM6 activity." (PMID 38279093, 2024). "We conducted a sliding window (window width = 2) haplotype-based analyses to examine the genetic associations of TRPM6 with risk of type 2 diabetes." (PMID 19149903, 2009). "Our results suggest that two common non-synonymous TRPM6 coding region variants might interact with magnesium intake in determining the risk of type 2 diabetes." (PMID 19149903, 2009). "If our finding is replicated in future studies, it will suggest that common genetic variation in the TRPM6 locus known to harbor severe mutations causing monogenic magnesium deficiency confers a modest susceptibility to the risk of type 2 diabetes in a small subgroup of the general population." (PMID 19149903, 2009). "Our results provide suggestive evidence that two common non-synonymous TRPM6 coding region variants, Ile1393Val and Lys1584Glu polymorphisms, might confer susceptibility to type 2 diabetes in women with low magnesium intake." (PMID 19149903, 2009). "We therefore conducted a prospective nested case-control study among postmenopausal women in the Women's Health Study to investigate the association between common variations of the TRPM6 and TRPM7 genes and the risk of type 2 diabetes." (PMID 19149903, 2009). "However, it is unclear whether common genetic variation in TRPM6 and TRPM7 contributes to risk of type 2 diabetes." (PMID 19149903, 2009). "Our haplotype analyses suggested a significant risk of type 2 diabetes among carriers of both the rare alleles from two non-synomous SNPs in TRPM6 (Val1393Ile in exon 26 [rs3750425] and Lys1584Glu in exon 27 [rs2274924]) when their magnesium intake was lower than 250 mg per day." (PMID 19149903, 2009).
colorectal cancer (5 papers, 2011 to 2025). A primary or metastatic malignant neoplasm that affects the colon or rectum. "TRPM6 is reported to be downregulated in colorectal cancer, with high expression related to better patient survival." (PMID 35309940, 2022). "Finally, genetic profile analysis in cancer samples targeted TRPM6 gene into 10 hub genes for colorectal cancer development and the regulation of its expression by the miRNA Hsa-let-7f-1 is key for patient survival." (PMID 33291725, 2020).
magnesium deficiency (5 papers, 2009 to 2021). A nutritional condition produced by a deficiency of magnesium in the diet, characterized by anorexia, nausea, vomiting, lethargy, and weakness. "In magnesium deficiency the expression of TRPM6 increases in the DCT, and the expression TRPM6/7 increases in the gut, leading to reduced urinary excretion and increased GI absorption." (PMID 29799851, 2018). "Clinical data show that sufficient magnesium intake can partially compensate for the severe magnesium deficiency caused by genetic defect in the TRPM6 gene." (PMID 19149903, 2009). "Third, althought serum magnesium may be a good indicator for heavy magnesium deficiency, we didn’t performed the measures of extracellular or intracellular magnesium status and the patch clamp experiment to display the effect on channel activity of studying polymorphic variant in TRPM6 gene." (PMID 27757375, 2016).
colon carcinoma (4 papers, 2015 to 2025). "This provided preliminary evidence for the role of TRPM6 deficiency in promoting the malignant progression of colon cancer." (PMID 41562086, 2025). "TRPM6 knockdown promoted colon cancer cell proliferation and migration, while concurrent TRPM6 knockdown and high Mg2+ treatment attenuated Mg2+-mediated tumor suppression." (PMID 41562086, 2025). "Little is known about the biophysical and pharmacological properties of TRPM7 and TRPM6 in cell lines of mammalian colon cancer or primary colon epithelial cells." (PMID 28810912, 2017). "We conclude that Mg homeostasis and the expression of two Mg channels, TRPM6 and 7, are altered in drug resistant colon carcinoma cells." (PMID 26563869, 2015). "Besides, colon cancer cells that are resistant to doxorubicin expressed lower amounts of TRPM6 and TRPM7." (PMID 31010205, 2019). "On these bases, TRPM6 and 7 are emerging as puzzling, potential players in colon cancer." (PMID 26563869, 2015).